GNG7 (G protein subunit gamma 7)
Description:
Guanine nucleotide-binding proteins (G proteins) are involved as a modulator or transducer in various transmembrane signaling systems. The beta and gamma chains are required for the GTPase activity, for replacement of GDP by GTP, and for G protein-effector interaction. Plays a role in the regulation of adenylyl cyclase signaling in certain regions of the brain. Plays a role in the formation or stabilization of a G protein heterotrimer (G(olf) subunit alpha-beta-gamma-7) that is required for adenylyl cyclase activity in the striatum (By similarity).
Synonyms: FLJ00058; HG3B
Tractability: Antibody: UniProt places it where antibodies can reach, with high confidence; its Gene Ontology location is reachable by antibodies, with high confidence. PROTAC: ubiquitination databases record sites on it; its protein half-life has been measured.
Gene: Protein-coding gene on chromosome 19 (2,511,214 to 2,702,724, reverse strand). Ensembl gene ENSG00000176533.
Subcellular location: Cell membrane
Pathways (Reactome):
Signal Transduction: Ca2+ pathway; Extra-nuclear estrogen signaling; G alpha (12/13) signalling events; G alpha (i) signalling events; G alpha (q) signalling events; G alpha (s) signalling events; G alpha (z) signalling events; G beta:gamma signalling through BTK; G beta:gamma signalling through CDC42; G beta:gamma signalling through PI3Kgamma; G beta:gamma signalling through PLC beta; G-protein activation; GPER1 signaling; Glucagon-type ligand receptors
Hemostasis: ADP signalling through P2Y purinoceptor 1; ADP signalling through P2Y purinoceptor 12; Prostacyclin signalling through prostacyclin receptor; Thrombin signalling through proteinase activated receptors (PARs); Thromboxane signalling through TP receptor
Metabolism: Adrenaline,noradrenaline inhibits insulin secretion; Glucagon signaling in metabolic regulation; Glucagon-like Peptide-1 (GLP1) regulates insulin secretion
Neuronal System: Activation of G protein gated Potassium channels; Inhibition of voltage gated Ca2+ channels via Gbeta/gamma subunits; Presynaptic function of Kainate receptors
Cellular responses to stimuli: High laminar flow shear stress activates signaling by PIEZO1 and PECAM1:CDH5:KDR in endothelial cells
Disease: ADORA2B mediated anti-inflammatory cytokines production
Metabolism of proteins: Cooperation of PDCL (PhLP1) and TRiC/CCT in G-protein beta folding
Transport of small molecules: Vasopressin regulates renal water homeostasis via Aquaporins
Gene Ontology:
Molecular function: protein binding; G-protein beta-subunit binding
Biological process: G protein-coupled receptor signaling pathway; regulation of G protein-coupled receptor signaling pathway
Cellular component: extracellular exosome; heterotrimeric G-protein complex; plasma membrane
Genetic constraint (gnomAD): Loss-of-function variants: 0 observed, 3.42 expected, observed/expected ratio (o/e) 0, 90% interval 0 to 0.87. That is too few expected variants to judge how well the gene tolerates losing a copy. Missense variants: 46 observed, 57.79 expected, observed/expected ratio (o/e) 0.8, 90% interval 0.63 to 1.02. Synonymous variants: 25 observed, 24.03 expected, observed/expected ratio (o/e) 1.04, 90% interval 0.76 to 1.45.
Homologues: Orthologues: chimpanzee GNG7 (100% identical), macaque GNG7 (100% identical), pig GNG7 (97% identical), mouse Gng7 (94% identical), rat Gng7 (94% identical), zebrafish gng7 (94% identical), guinea pig GNG7 (93% identical), tropical clawed frog gng7 (88% identical). Paralogues in human: GNG12 (76% identical), GNG2 (71% identical), GNG4 (63% identical), GNG3 (62% identical), GNG8 (53% identical), GNG10 (50% identical), GNG5 (47% identical), GNG5B (44% identical), GNGT2 (40% identical), GNG11 (35% identical), GNGT1 (34% identical).
Diseases named in the same sentence as GNG7 in open-access papers:
GNG7 is named in the same sentence as 77 diseases in open-access papers, as found by Europe PMC text mining. Sharing a sentence is not in itself a finding about the gene and the disease. The quoted sentences say what the papers report.
esophageal cancer (13 papers, 2013 to 2024). A primary or metastatic malignant neoplasm involving the esophagus. "GNG7, G protein subunit gamma 7, is a protein encoding gene and the reduced expression of it is associated with squamous cell carcinoma and esophageal cancer." (PMID 34034637, 2021). "Previous studies have reported that the loss of GNG7 is related to the tumor volume of esophageal cancer and affects tumor invasiveness, which may attributed to loss of heterozygosity (LOH)." (PMID 35281820, 2022). "For instance, the survival rate of patients with high GNG7 expression is significantly higher than that of patients with low GNG7 expression in esophageal cancer, and low GNG7 expression leads to a deeper invasion in vitro and in vivo." (PMID 39104385, 2024). "Previous studies have shown a correlation between reduced expression of Gng7 and breast cancer, lung cancer, head and neck cancer, and esophageal cancer." (PMID 38089628, 2023). "Many studies have shown that GNG7 is a tumor suppressor gene in squamous cell carcinoma, pancreatic cancer, esophageal cancer, gastrointestinal cancer and clear cell renal cell carcinoma." (PMID 36147484, 2022). "GNG7 is frequently downregulated in various cancers including pancreatic cancer, esophageal cancer and clear cell renal cell carcinoma." (PMID 36159963, 2022). "Recent studies demonstrated that GNG7 is frequently down-regulated in various cancers, such as esophageal cancer, head and neck carcinoma, pancreatic cancer, and renal carcinoma." (PMID 34635014, 2021). "They found that GNG7 was downregulated in pancreatic cancer, gastric cancer, intrahepatic cholangiocarcinoma, esophageal cancer, and CRC." (PMID 31737678, 2019). "Another study demonstrated that GNG7 suppression presented with worse survival outcomes, which may result from promoter hypermethylation in esophageal cancer." (PMID 39104385, 2024). "Remarkably, GNG7 has been repeatedly shown to function as a tumor suppressor in many human cancers, including head and neck squamous cell carcinoma, esophageal cancer, breast cancer, pancreatic cancer, intrahepatic cholangiocarcinoma, clear cell renal cell carcinoma, and Hodgkin lymphoma." (PMID 36863706, 2023). "GNG7 gene has a highly methylated promoter in squamous cell carcinoma of the head and neck and esophageal cancer, however, the effect and underlying mechanism of GNG7 loss and the function on cancer biology in ccRCC remain unknown." (PMID 30945310, 2019). "However, the GNG7 expression-induced progression of esophageal cancer may be attributed to the hypermethylation of GNG7 promoter." (PMID 37704946, 2023).
clear cell renal cell carcinoma (12 papers, 2020 to 2024). "A previous study showed that GNG7 was down-regulated in clear cell renal cell carcinoma tissues due to promoter methylation and frequent gene mutations, and negatively associated with overall survival." (PMID 34650124, 2021). "In clear cell renal cell carcinoma, cells with lower GNG7 level exhibit an increase in G2/M cell cycle phase." (PMID 34221006, 2021). "Additionally, GNG7 is downregulated in clear cell renal cell carcinoma and positively correlates with overall survival of patients, implying a protective role of GNG7." (PMID 39104385, 2024). "Our hypothesis posits that GNG7, serving as a potential biomarker in clear cell renal cell carcinoma (CCRCC), could significantly influence the oncogenesis and progression of tumor disease by actively participating in the regulation of the immune system." (PMID 37704946, 2023). "Moreover, it has been reported that GNG7 is a tumor suppressor gene in clear cell renal cell carcinoma and a lower expression of GNG7 predicts poor overall survival outcomes." (PMID 33619235, 2021). "GNG7 (G protein subunit gamma 7), a novel possible tumor suppressor gene, is proved to be down-regulated in various carcinoma, including head and neck squamous cell carcinoma, clear cell carcinoma of kidney, pancreatic cancer, oesophageal cancer, lung adenocarcinoma." (PMID 33287749, 2020).
pancreatic cancer (11 papers, 2019 to 2023). "OPRM1 and GNG7 were reported to be associated with oesophageal cancer and pancreatic cancer, respectively." (PMID 31640538, 2019). "Multiple studies have shown that GNG7 expression is decreased in many cancers, including pancreatic cancer, gastrointestinal tract cancer and renal carcinoma." (PMID 36159963, 2022). "G protein γ subunit 7 (GNG7), a member of large G γ family, has been reported to be downregulated in various cancers including pancreatic cancer, oesophageal cancer, and gastrointestinal tract cancer." (PMID 34221006, 2021).
breast cancer (10 papers, 2019 to 2024). A primary or metastatic malignant neoplasm involving the breast. "The down-regulation of ADHFE1, and GNG7 was associated with poor prognosis in breast cancer patients (p < 0.05)." (PMID 36969015, 2023). "Additionally, previous studies showed that reduced expression of GNG7 was associated with breast cancer, lung carcinogenesis, head and neck cancer and esophageal cancer." (PMID 34650124, 2021). "The study revealed that, compared to normal breast tissue, GNG7 exhibits lower expression in breast cancer tissue." (PMID 38539064, 2024). "Silencing GNG7 significantly enhances cell proliferation, inhibits apoptosis, and the exogenous overexpression of GNG7 has a reversing effect on breast cancer cells." (PMID 38539064, 2024). "Decreased GNG7 expression has been detected in multiple tumors, including head and neck squamous epithelial tumors, breast cancer (BC), gastric cancer (GC), kidney cancer, colorectal cancer (CRC) and lung adenocarcinoma (LUAD)." (PMID 37704946, 2023). "The analysis uncovered that GNG7 expression was significantly related to the prognosis of eight types of tumors including lung cancer, breast cancer and colorectal cancer." (PMID 35281820, 2022). "Our findings of gene expression and breast cancer prognosis were consistent with the previous evidence for HSP90AA1, ADCY4, and GNG7." (PMID 35729536, 2022). "Network analysis on the cancer genome atlas (TCGA) breast cancer dataset revealed interaction between CXCL12 and CXCR7 (ACKR3), and a number of G-protein family members (GNG5, GNB4, GNB2, GNG12, GNG7, GNGT1, and GNAI3)." (PMID 30993013, 2019).
gastric cancer (8 papers, 2019 to 2024). A primary or metastatic malignant neoplasm involving the stomach. "GNG7, MXRA7, ASB2, and CHMP4C are also involved in the development of lung cancer, gastric cancer, colorectal cancer, and cervical cancer, respectively." (PMID 36225190, 2022). "In summary, LINC01526 promoted gastric cancer progression by interacting with TARBP2, which subsequently degraded GNG7 mRNA." (PMID 36230863, 2022). "Finally, the rescue assay disclosed that LINC01526 promoted gastric cancer progression by interacting with TARBP2, leading to the degradation of GNG7 mRNA." (PMID 36230863, 2022).
colorectal cancer (7 papers, 2021 to 2025). A primary or metastatic malignant neoplasm that affects the colon or rectum. "GNG7 encodes guanine nucleotide-binding protein γ−7, whose expression level was associated with the infiltration of multiple immune cells into human colorectal cancer samples." (PMID 36009735, 2022). "Moreover, KEGG enrichment analysis of GNG7-related genes was conducted, which suggested that the ERBB signaling pathway was related to the immune status mediated by GNG7, and the Colorectal cancer pathway was associated with the tumor status mediated by GNG7." (PMID 37704946, 2023). "Notably, In the GSE17536 and GSE17537 cohorts, which included 177 and 55 colorectal cancer samples respectively, high GNG7 expression was associated with better OS (p = 0.034, HR = 0.08,95%CI 0.01–0.83) and DSS (Disease Specific Survival, p = 0.031, HR = 0.28,95%CI 0.09–0.89)." (PMID 35281820, 2022). "A total of 150 genes were identified as MRGs from CRC analysis which includes PDX1 and GNG7 as spotlight genes were consistently found in rectal as well as colorectal cancer samples in both differentially expressed and methylated gene groups." (PMID 40565513, 2025). "GNG7 was a promising prognostic biomarker and was related to immune cell infiltration in colorectal cancer." (PMID 36969015, 2023). "In addition, the findings from UALCAN indicated that GNG7 expression is associated with tumor histology, stage, lymph node metastasis in colorectal cancer which means that GNG7 may play an important role in the occurrence and progression of colorectal cancer." (PMID 35281820, 2022). "Another important part of this study is to explore the correlation between the expression of GNG7 and the level of infiltration of different immune cells as well as immunoregulators in cancer, especially in colorectal cancer." (PMID 35281820, 2022). "Our study confirmed that GNG7 expression is down-regulated in colorectal cancer, and GNG7 expression is related to the prognosis of colorectal cancer." (PMID 35281820, 2022). "In our study, we identified GNG7 as being downregulated and hypomethylated in colorectal cancer." (PMID 40565513, 2025). "Moreover, we investigated the correlation between GNG7 expression and immune infiltration as well as immunoregulation level in colorectal cancer via TIMER, TISIDB, and GEPIA databases." (PMID 35281820, 2022). "Therefore, we can conclude that GNG7 may be a potential biomarker and is related to the immune infiltration of colorectal cancer, which means that GNG7 can be used as a potential target for regulating anti-tumor immunotherapy." (PMID 35281820, 2022). "However, the role of GNG7 in colorectal cancer remains to be elucidated." (PMID 35281820, 2022). "However, the correlation between GNG7 expression and immune infiltration as well as patient prognosis of colorectal cancer (CRC) remains unclear." (PMID 35281820, 2022). "In total, 150 genes were inferred as methylation-regulated genes (MRGs) across the total colorectal cancer cohort, with two genes in particular—PDX1 and GNG7—consistently identified in both rectal and colon cancer individual analyses." (PMID 40565513, 2025). "This study aims to predict the role of GNG7 in CRC by studying the relationship between the expression level of GNG7 and the infiltration level of different immune cells in colorectal cancer and the prognosis of patients with CRC through multi-channel bioinformatics data mining and analysis." (PMID 35281820, 2022). "CircFMN2/miR-1182 may also regulate the progression of colorectal cancer by targeting CD44, GNG7, RB1, COL1A2, PLCB1, SLC17A7, and TERT." (PMID 34249673, 2021).
lung adenocarcinoma (7 papers, 2020 to 2025). A carcinoma that arises from the lung and is characterized by the presence of malignant glandular epithelial cells. "Ultimately, validating the correlation between GNG7 expression levels and immune therapy responses through clinical studies will provide personalized and combinational treatment options for lung adenocarcinoma patients." (PMID 40496619, 2025). "Future research should aim to deepen our understanding of how GNG7 regulates immune responses at the molecular level, including its role in immune escape in lung adenocarcinoma." (PMID 40496619, 2025). "On the contrary, EBF1 (z = −11.34) and GNG7 (z = −5.813) were the brain neuroblastoma- and lung adenocarcinoma-specific positive prognostic genes, respectively." (PMID 35634306, 2022). "Nevertheless, the role of GNG7 in lung adenocarcinoma (LUAD) remains unclear." (PMID 34635014, 2021).
lung carcinoma (7 papers, 2020 to 2025). "In the GSE31210 cohort which included 204 lung cancer samples, high GNG7 expression was associated with better OS (Overall Survival, p = 0.0005, HR = 0.29,95%CI 0.14–0.58) and RFS (p = 0.0002, HR = 0.25,95%CI 0.13–0.49)." (PMID 35281820, 2022). "Previous studies have reported GNG7 downregulation in various cancers, including pancreatic, gastrointestinal tract, renal, and lung cancers." (PMID 40565513, 2025). "Then, we detected mRNA and protein levels of GNG7 in multiple lung cancer cell lines and normal bronchial epithelial cell line (16HBE)." (PMID 34635014, 2021). "Inhibition of Cyclin K with siRNA significantly reduced basal expression levels of Cyclin D1 and GNG3, while increasing expression levels of PCDH9, WNT9A and GNG7 in two different lung cancer cell lines." (PMID 33042275, 2020). "Besides, as a possible novel tumor suppressor gene, the elucidating mechanism of GNG7 in tumor genesis and progression will deepen our understanding of carcinomas including lung cancer and have great theoretical and scientific significance." (PMID 33287749, 2020).